INS (insulin)
Diseases named in the same sentence as INS in open-access papers (continued):
Sharing a sentence is not in itself a finding about the gene and the disease.
metabolic syndrome (continued). "Because muscle is the main tissue responsible for insulin mediated glucose disposal, sarcopenia and related conditions can then promote insulin resistance, type 2 diabetes, dyslipidemia, hypertension and metabolic syndrome." (PMID 24587226, 2014). "Guar gum treatment decreased markers of the metabolic syndrome (body weight, adipose weight, triglycerides, glucose and insulin levels and HOMA-IR) in a dose-dependent manner." (PMID 25203112, 2014). "For metabolic syndrome assessment, fasting plasma glucose and insulin were measured and oral glucose tolerance test was performed throughout the treatment period." (PMID 25045706, 2014). "In fact, FATP1 gene knockout in mice protects against high-fat diet-induced reduction of insulin-stimulated whole-body glucose turnover; and impairment of insulin tolerance and signs of metabolic syndrome." (PMID 24858472, 2014). "In conclusion, AT1R blockade attenuated several metabolic and cardiovascular disturbances, including dyslipidemia, glycemic alterations and insulin resistance, and phenotypical responses in myocardial tissue from obese animals." (PMID 24466104, 2014). "NAFLD is the hepatic manifestation of metabolic syndrome, and its appearance and development is directly related to a deficit in insulin signaling, both in the liver and the whole organism." (PMID 25533006, 2014). "The authors intended to determine the relationship between resistin and insulin sensitivity, body fat distribution and the metabolic syndrome in humans." (PMID 24692844, 2014). "Metabolic syndrome is defined as a concurrence of disturbed glucose and insulin metabolism, abdominal fat, dyslipidemia, and hypertension." (PMID 25309758, 2014). "Recent clinical observations revealed that SIRT1 expression in peripheral blood mononuclear cells (PBMCs) from metabolic syndrome and insulin resistant subjects was significantly reduced compared with controls." (PMID 24624081, 2014). "These clinically relevant models indicate the significance of certain nutrients in inducing undesirable adverse effects on metabolic syndrome and liver function, especially on insulin elimination and glucose and lipid metabolism." (PMID 25101998, 2014). "Human randomized controlled clinical trials showed that guar gum supplementation decreased body weight and fasting plasma glucose and insulin concentrations in both healthy and metabolic syndrome patients." (PMID 25203112, 2014). "PPARγ agonists regulate multiple processes, including Aβ homeostasis through the suppression of BACE1 expression, energy metabolism, insulin sensitivity, dyslipidemia, and microglial inflammatory responses." (PMID 25356910, 2014). "Understanding the effect of the intestinal microbiome on the pathogenesis of metabolic syndrome and insulin is of utmost importance in developing alternative approaches to therapy." (PMID 24778627, 2014). "Following treatment, oxygen expenditure was assessed using indirect calorimetry, while glucose tolerance, insulin sensitivity, and indices of dyslipidemia were assessed by serum biochemistry." (PMID 25114710, 2014). "Metabolic syndrome (MS) designates a group of cardiac risk factors consisting of insulin resistance (IR) (impaired insulin action), visceral obesity, atherogenic dyslipidemia, endothelial dysfunction, and systemic inflammation." (PMID 24619122, 2014). "Abnormal increase in intrahepatic lipid metabolites content directly inhibits insulin-stimulated glucose transport activity in the organ, with major implications for the onset of liver dysmetabolism in the metabolic syndrome." (PMID 25905030, 2014). "The present study aimed to evaluate the effects of butter naturally enriched in cis-9, trans-11 CLA on parameters related to glucose tolerance, insulin sensitivity and dyslipidemia in rats." (PMID 25534067, 2014).
metabolic syndrome (continued). "The metabolic syndrome insulin responsiveness quantified by euglycemic insulin clamp studies was less than half that seen in age‐ and gender‐matched sedentary control subjects." (PMID 25472611, 2014). "Metabolic syndrome (MetS) is characterized by a combination of disturbed glucose and insulin metabolism, central obesity, dyslipidemia, and hypertension." (PMID 23339671, 2013). "An increase in insulin sensitivity and a reduction of ER stress has been observed in obese patients following gastric bypass surgery, suggesting a link in clinical metabolic syndrome." (PMID 23840313, 2013). "Components of the metabolic syndrome, such as inflammatory markers and insulin sensitivity, have also been used to categorize subjects as metabolically healthy or unhealthy." (PMID 24039900, 2013). "We sought to examine the relationship of chemerin with metabolic syndrome disturbances including body fat percentage, serum lipid, glucose, insulin levels and body fat percentage in lean and obese volunteers." (PMID 23468920, 2013). "Post-term children have reduced insulin sensitivity and display a number of early markers of the metabolic syndrome." (PMID 23840881, 2013). "High plasma levels of insulin and glucose are two of the major manifestations of metabolic syndrome." (PMID 23437093, 2013). "The observed improvement in insulin sensitivity among girls born to older mothers would support this assertion, as a reduction in insulin sensitivity is predictive of the metabolic syndrome in adulthood." (PMID 23527040, 2013). "Non-alcoholic fatty liver disease (NAFLD), the hepatic manifestation of the metabolic syndrome, is a complex multifactorial disease characterized by metabolic deregulations that include accumulation of lipids in the liver, lipotoxicity, and insulin resistance." (PMID 23346097, 2013). "Even moderately increased iron stores, represented by high-normal ferritin concentrations, are associated with adverse health conditions, such as hypertension, dyslipidemia, elevated fasting insulin and blood glucose, and central adiposity." (PMID 24066115, 2013). "Good control of metabolic syndrome was helped by diet results with the insulin-sensitizing supplements and the related primary prevention of breast cancer." (PMID 23981814, 2013). "In conclusion, our study shows that pre-pubertal children born post-term have lower insulin sensitivity and a number of early markers of the metabolic syndrome." (PMID 23840881, 2013). "In insulin sensitive tissues (liver, skeletal muscle and adipose tissue) and pancreatic β-cells obtained from the well-known metabolic syndrome model (Zucker Diabetic Fatty rat, ZDF), altered gene expression pattern were shown when compared to their controls." (PMID 23320804, 2013). "Nevertheless, the key implications are that youths with high insulin and HOMA-IR levels have a much greater risk of being classified with metabolic syndrome." (PMID 24228769, 2013). "The KK-Ay mouse strain is glucose intolerant, severely insulin resistant, dyslipidemic, and hypertensive; all are characteristics of the “metabolic syndrome” phenotype of T2D patients." (PMID 23710468, 2013). "Recently, several hormones secreted by adipose tissue have been determined to be involved in overall insulin sensitivity in metabolic syndrome-related conditions, including adipocyte fatty-acid binding protein (A-FABP)." (PMID 23375099, 2013). "The “metabolic syndrome” involves many biological systems, but insulin sensitivity or resistance is perhaps the area subject to the most detail study in later life." (PMID 23662104, 2013). "Despite the unquestionable success of HAART, prevalence of DM, insulin resistance, blood pressure fat redistribution and mainly dyslipidemia have substantially increased after its global scaling up." (PMID 24330597, 2013).
metabolic syndrome (continued). "They postulate that healthy bone matrix protein increases insulin sensitivity in other tissues and that people with metabolic syndrome who are insulin resistant also have poorer bone quality and increased risk of osteoporotic fracture." (PMID 23662104, 2013). "Aging also impairs AMPK activation and suppresses insulin-stimulated glucose uptake into rat skeletal muscles, which is held to enhance the development of metabolic syndrome." (PMID 23883619, 2013). "The accumulated fat molecules inhibit insulin signaling and lead to increase in the levels of insulin in bloodto maintain homeostasis, and this compensatory hyperinsulinemiadamages various organs in metabolic syndrome." (PMID 23840225, 2013). "Since insulin sensitivity is influenced by and associated with other factors such as excess adiposity and dyslipidemia, we hypothesize that a combination of simple anthropometric and biochemical parameters might provide a better estimate of insulin sensitivity than HOMA-IR." (PMID 24098646, 2013). "Salicylate, an inhibitor of IKK has been shown to reverse hyperglycemia, hyperinsulinemia, and dyslipidemia in obese rodents by sensitizing insulin signaling." (PMID 23675368, 2013). "All % BF values obtained in the study maintained their association with TG, insulin, and HOMA-IR, which are components of the metabolic syndrome, with R2 ranging from 0.07 to 0.19 depending on the parameter evaluated." (PMID 23762051, 2013). "Metabolic syndrome (MetS) - a clustering of disturbed glucose and insulin metabolism, obesity or abdominal adiposity, dyslipidaemia, and hypertension, is an important risk factor for cardiometabolic diseases." (PMID 23886070, 2013). "Studying only the control pigs as a model for metabolic syndrome when fed the two diets showed correlations to the same parameters but now more focused on insulin, glucose and abdominal fat depot parameters." (PMID 24086269, 2013). "The metabolic syndrome (MetS) has been defined as a constellation of risk factors, including obesity, high levels of triglycerides, low levels of high-density lipoprotein cholesterol, elevated serum levels of fasting plasma insulin, and hypertension." (PMID 23476647, 2013). "We have then assessed the effect of glucagon-like peptide 1 (GLP-1), a gut peptide that stimulates insulin secretion and sensitivity, on insulin-stimulated vascular reactivity in patients with the metabolic syndrome." (PMID 24177571, 2013). "Metabolic syndrome was evaluated testing plasma glucose, triglycerides, cholesterol, insulin, and glucose tolerance." (PMID 23593350, 2013). "This was first demonstrated in OC knockout mice, which develop a metabolic syndrome that includes high blood glucose, low serum insulin concentrations, and poor glucose tolerance." (PMID 24340022, 2013). "It has previously been shown to play a central role in the pathogenesis of metabolic syndrome and to be involved in insulin-stimulated Glut4 trafficking." (PMID 23825961, 2013). "The animals experienced characteristic changes that include increased body weight, glucose intolerance, increased serum insulin levels, and dyslipidemia." (PMID 23561047, 2013). "In our present study, a regulator gene of insulin action, the insulin responsive sequence DNA binding protein-1 showed down-regulation in metabolic syndrome in ZDF rat hearts." (PMID 23320804, 2013). "We investigated the effects of an isocaloric healthy Nordic diet on insulin sensitivity, lipid profile, blood pressure and inflammatory markers in people with metabolic syndrome." (PMID 23398528, 2013). "In the present study, the metabolic syndrome criteria provides groupings that are reinforced by multiple variables, one of which being insulin sensitivity." (PMID 24358323, 2013). "Conversely, knockdown of 11β-HSD1 in mice results in protection from high-fat diet-induced development of the metabolic syndrome, including reduced adiposity and improved insulin sensitivity." (PMID 24022868, 2013).
metabolic syndrome (continued). "As shown in our study, administration of Lr263 dramatically decreased the levels important components of metabolic syndrome, including serum glucose, insulin, LDL, TG, and cholesterol, enhanced by high fructose treatment." (PMID 23590862, 2013). "Obese children were several times more likely than normal-weight children to have hypertension, high insulin, dyslipidemia and high uric acid." (PMID 23984682, 2013). "More recently, the CAPITAIN study showed that 6-month treatment with pitavastatin 4 mg did not significantly change the mean FPG, homeostasis model assessment index, insulin levels, insulin/glucose ratios, or HbA1c levels in people with metabolic syndrome." (PMID 23819776, 2013). "The improved endothelial function and insulin sensitivity observed in the supplemented groups confirms the role of antioxidant vitamins in the management of metabolic syndrome." (PMID 22953063, 2012). "The results of some studies have shown that low dose of Flutamide/ Metformin/ Oral Contraceptive Pill (OCP) in young PCOS patients with normal weight improves the resistance to insulin and dyslipidemia which are long-term side effects of PCOS administration." (PMID 25505514, 2012). "The waist circumference cut points for diagnosing metabolic syndrome (as defined using the new harmonised guidelines), insulin resistance, dysglycaemia, hypertension and dyslipidaemia were obtained using receiver operator characteristic curve analysis." (PMID 23145009, 2012). "Visceral adiposity seems to be an independent predictor of insulin sensitivity, impaired glucose tolerance, dyslipidemia and elevated blood pressure." (PMID 26557292, 2012). "Thiazolidinediones (TZDs) have been shown to act as insulin sensitizers and used as therapeutic agents for the treatment of dyslipidemia and type II diabetes, both common occurrences in CKD." (PMID 22537670, 2012). "Prolonged ovariectomy resulted in dyslipidemia, impaired glucose tolerance and insulin-stimulated skeletal muscle glucose transport, as compared to SHAM." (PMID 22463706, 2012). "The low-carbohydrate group experienced significantly more weight loss and reduction in adipose tissue, improved blood glucose levels and insulin sensitivity, and increases in HDL, all risk factors for metabolic syndrome and breast cancer recurrence." (PMID 23050155, 2012). "Elevated levels of triglycerides, insulin, glucose, and IGF-1 have all been suggested as contributing to the association of the metabolic syndrome with increased risk of colorectal cancer." (PMID 22127286, 2012). "This study showed a reduction of GLUT4 protein content of insulin-sensitive tissues in an animal model of metabolic syndrome, a fundamental mechanism to impair glucose uptake and glucose homeostasis." (PMID 22897936, 2012). "IGFBP2 concentrations correlate with insulin sensitivity, and low levels of this protein are a marker for the metabolic syndrome." (PMID 23781310, 2012). "In persons with obesity, cardiometabolic pathogenesis occurs prematurely, and is accelerated by factors that are likely to be a combination of the established risk factors, as well as underlying insulin and glucose metabolic dysfunction associated with prediabetes and metabolic syndrome (MetS)." (PMID 25309821, 2012). "The key findings support that the antidiabetic actions of berberine include increasing secretion of insulin, improving insulin resistance, and ameliorating dyslipidemia." (PMID 23118793, 2012). "We propose that components of the metabolic syndrome and the insulin-leptin-adiponectin axis play a pivotal role in the pathogenesis and progression of TNBC." (PMID 22295251, 2012). "The intake of this fiber type can reduce glycemia from lower absorption and digestion of carbohydrates, thus reducing insulin secretion, in addition to reducing dyslipidemia." (PMID 22417631, 2012).
metabolic syndrome (continued). "Metformin, which works by sensitizing patients to insulin to lower circulating glucose and insulin levels, further connects metabolic syndrome with treatment outcomes in breast cancer." (PMID 23050155, 2012). "After 3 months of fructose feeding, FFR groups manifested features of metabolic syndrome, including a significant increase in the fasting insulin, triglyceride, and cholesterol levels of the blood." (PMID 23029112, 2012). "The possible mechanism of how high salt diet induces metabolic syndrome responses is that salt does not only increase the blood pressure but also decreases insulin sensitivity in Dahl salt-sensitive rats." (PMID 22953063, 2012). "HFD and saturated fatty acid intake correlate with Metabolic Syndrome; while polyunsaturated fatty acids have been shown to improve insulin sensitivity, as well as lessen inflammation." (PMID 22701716, 2012). "Studies have emphasized the fact that adiponectin, which is secreted from the adipose tissue and is known to increase insulin sensitivity, is found in remarkably low concentrations in patients with metabolic syndrome." (PMID 23261860, 2012). "Plasma adiponectin concentration was less in dogs with metabolic syndrome (P = 0.031), whilst plasma insulin concentration was greater (P = 0.030), and they were negatively correlated with one another (Kendall’s tau -0.29, P = 0.016)." (PMID 22929809, 2012). "We have previously shown, that in response to an insulin-sensitizing agent given to metabolic syndrome normoglycemic patients, there was a concomitant improvement in skin microvascular dysfunction and in endothelial microvascular reactivity in the muscle." (PMID 23148545, 2012). "Inducers of GLUT4 translocation or expression were found to exert their beneficial effects on sensitizing insulin signal and recovering the dys-regulated gene expressions, eventually resulting in amelioration of metabolic syndrome." (PMID 22384078, 2012). "Previous studies have stressed the fact that the levels of adiponectin, which is secreted from the adipose tissue and is known to increase insulin sensitivity, are remarkably low in cases with metabolic syndrome." (PMID 23261860, 2012). "The dietary balance of the ratios of n-6 to n-3 PUFA affects the regulation of metabolic functions and the development of metabolic syndrome, including lipid profile and adiposity, insulin sensitivity and inflammation." (PMID 22963037, 2012). "Given the fact that it seems NASH is a part of metabolic syndrome, the effects of these drugs on lipid profile, blood sugar, serum insulin level, and HOMA Index were also examined in addition to their effects on decrease in hepatic aminotransferases." (PMID 23087748, 2012). "In both men and women, blood pressure, triglycerides, HDL-cholesterol, C reactive protein, adiponectin, fasting glucose and insulin were significantly different in metabolic syndrome compared to non-metabolic syndrome individuals." (PMID 23028366, 2012). "The amount of epicardial fat is directly related to the increases in visceral fat, insulin resistance, triglyceride levels and blood pressure, and in general with the metabolic syndrome." (PMID 22701195, 2012). "In conclusion, this study indicates that Iberian pigs freely eating saturated fat diets are prone to central obesity, abnormalities in insulin-glucose regulation, dyslipidemia, and elevated blood pressure, the symptoms of metabolic syndrome." (PMID 22629144, 2012). "The effect of n-3 PUFAs on insulin as a mediator of the metabolic syndrome needs to be clarified, but there is some support for a relationship between the content of n-3 PUFAs in cell membranes and the action of insulin." (PMID 23304630, 2012). "Adiponectin, an adipocitokine, plays a significant role in T2DM and metabolic syndrome, due to its insulin sensitizing anti-inflammatory and anti-atherogenic properties." (PMID 22174491, 2011).